MIR596 (microRNA 596)
Synonyms: hsa-mir-596; MIRN596
Gene: MicroRNA gene on chromosome 8 (1,817,231 to 1,817,307, forward strand). Ensembl gene ENSG00000207826.
Diseases named in the same sentence as MIR596 in open-access papers:
MIR596 is named in the same sentence as 1 disease in open-access papers, as found by Europe PMC text mining. Sharing a sentence is not in itself a finding about the gene and the disease. The quoted sentences say what the papers report.
prostatic cancer (1 paper, 2025). "In the literature, epigenetic inactivation of MIR596 is associated with prostatic cancer, while its overexpression has been shown to deregulate Wnt-β-catenin signaling." (PMID 41339323, 2025).